CHRNA1 (cholinergic receptor nicotinic alpha 1 subunit)
Description:
[Isoform 1]: Upon acetylcholine binding, the AChR responds by an extensive change in conformation that affects all subunits and leads to opening of an ion-conducting channel across the plasma membrane. [Isoform 2]: Non functional acetylcholine receptor alpha subunit which is not integrated into functional acetylcholine-gated cation-selective channels.
Synonyms: ACHRA; ACHRD; CHRNA; CMS1A; CMS1B; CMS2A; FCCMS; SCCMS
Tractability: Small molecule: an approved drug acts on it; a structure with a bound ligand is known; a high-quality ligand is known; it belongs to a druggable protein family. Antibody: UniProt places it where antibodies can reach, with high confidence; its Gene Ontology location is reachable by antibodies, with high confidence; UniProt predicts a signal peptide or a membrane-spanning region; the Human Protein Atlas places it where antibodies can reach. PROTAC: a small molecule that binds it is known.
Target class: Ion channel; Nicotinic acetylcholine receptor alpha subunit; Ligand-gated ion channel; Nicotinic acetylcholine receptor
Safety:
Unwanted effects reported when the protein is acted on. In parentheses: how it was acted on, where the effect was seen, and who reports it.
abuse potential (activation; cardiovascular system, central nervous system, pulmonary, gastrointestinal; source: Bowes et al. (2012))
analgesia (activation; cardiovascular system, central nervous system, pulmonary, gastrointestinal; source: Bowes et al. (2012))
analgesic effects (activation; cardiovascular system, nervous system, respiratory, gastrointestinal; source: Urban et al. (2012))
antihypertensive agent (inhibition; cardiovascular system, nervous system, respiratory, gastrointestinal; source: Urban et al. (2012))
apnoea (inhibition; cardiovascular system, central nervous system, pulmonary, gastrointestinal; source: Bowes et al. (2012))
autonomic effects (activation; cardiovascular system, nervous system, respiratory, gastrointestinal; source: Urban et al. (2012))
cardiovascular effects (activation; cardiovascular system, nervous system, respiratory, gastrointestinal; source: Urban et al. (2012))
cognitive effects (activation; cardiovascular system, nervous system, respiratory, gastrointestinal; source: Urban et al. (2012))
constipation (inhibition; cardiovascular system, central nervous system, pulmonary, gastrointestinal; source: Bowes et al. (2012))
decreased blood pressure (inhibition; cardiovascular system, central nervous system, pulmonary, gastrointestinal; source: Bowes et al. (2012))
decreased heart rate (inhibition; cardiovascular system, central nervous system, pulmonary, gastrointestinal; source: Bowes et al. (2012))
dopaminergic modulation (activation; cardiovascular system, nervous system, respiratory, gastrointestinal; source: Urban et al. (2012))
gastrointestinal effects (activation; cardiovascular system, nervous system, respiratory, gastrointestinal; source: Urban et al. (2012))
glutamatergic modulation (activation; cardiovascular system, nervous system, respiratory, gastrointestinal; source: Urban et al. (2012))
increased heart rate (activation; cardiovascular system, central nervous system, pulmonary, gastrointestinal; source: Bowes et al. (2012))
motor effects (activation; cardiovascular system, nervous system, respiratory, gastrointestinal; source: Urban et al. (2012))
muscle relaxant (inhibition; cardiovascular system, nervous system, respiratory, gastrointestinal; source: Urban et al. (2012))
muscle relaxation (inhibition; cardiovascular system, central nervous system, pulmonary, gastrointestinal; source: Bowes et al. (2012))
nausea (activation; cardiovascular system, central nervous system, pulmonary, gastrointestinal; source: Bowes et al. (2012))
palpitations (activation; cardiovascular system, central nervous system, pulmonary, gastrointestinal; source: Bowes et al. (2012))
paralysis (activation; cardiovascular system, central nervous system, pulmonary, gastrointestinal; source: Bowes et al. (2012))
respiratory effects (activation; cardiovascular system, nervous system, respiratory, gastrointestinal; source: Urban et al. (2012))
serotoninergic modulation (activation; cardiovascular system, nervous system, respiratory, gastrointestinal; source: Urban et al. (2012))
Gene: Protein-coding gene on chromosome 2 (174,747,592 to 174,787,935, reverse strand). Ensembl gene ENSG00000138435.
Subcellular location: Postsynaptic cell membrane; Cell membrane
Subcellular location (Human Protein Atlas): Plasma membrane
Pathways (Reactome):
Neuronal System: Highly calcium permeable nicotinic acetylcholine receptors; Highly calcium permeable postsynaptic nicotinic acetylcholine receptors
Gene Ontology:
Molecular function: acetylcholine-gated monoatomic cation-selective channel activity; transmitter-gated monoatomic ion channel activity involved in regulation of postsynaptic membrane potential; acetylcholine binding; acetylcholine receptor activity; neurotransmitter receptor activity; extracellular ligand-gated monoatomic ion channel activity; monoatomic ion channel activity; transmembrane signaling receptor activity
Biological process: muscle cell cellular homeostasis; musculoskeletal movement; neuromuscular junction development; neuromuscular process; neuromuscular synaptic transmission; neuron cellular homeostasis; neuronal action potential; regulation of membrane potential; skeletal muscle contraction; skeletal muscle tissue growth; acetylcholine receptor signaling pathway; calcium ion transport; membrane depolarization; monoatomic ion transmembrane transport; presynaptic modulation of chemical synaptic transmission; response to nicotine; synaptic transmission, cholinergic; cell communication; chemical synaptic transmission, postsynaptic; excitatory postsynaptic potential; monoatomic cation transport; monoatomic ion transport; regulation of postsynaptic membrane potential; signaling
Cellular component: acetylcholine-gated channel complex; cell surface; neuromuscular junction; plasma membrane; neuron projection; postsynaptic membrane; synapse; membrane; postsynaptic specialization membrane; presynapse
Genetic constraint (gnomAD): Loss-of-function variants: 35 observed, 49.21 expected, observed/expected ratio (o/e) 0.71, 90% interval 0.54 to 0.94. The upper end of that interval is the gene's LOEUF score, 0.94, which puts it in group 4 of 6, group 1 being the genes least tolerant of losing a copy. Missense variants: 506 observed, 621.01 expected, observed/expected ratio (o/e) 0.81, 90% interval 0.76 to 0.88. Synonymous variants: 229 observed, 236.48 expected, observed/expected ratio (o/e) 0.97, 90% interval 0.87 to 1.08.
Gene-disease validity (ClinGen):
ClinGen rates the evidence that CHRNA1 causes each of these diseases.
myasthenic syndrome, congenital, 1B, fast-channel (autosomal recessive): Definitive.
Homologues: Orthologues: chimpanzee CHRNA1 (99% identical), macaque CHRNA1 (98% identical), dog CHRNA1 (96% identical), pig CHRNA1 (96% identical), guinea pig CHRNA1 (95% identical), mouse Chrna1 (94% identical), rat Chrna1 (94% identical), rabbit CHRNA1 (83% identical), tropical clawed frog chrna1.2 (77% identical), zebrafish chrna1 (77% identical). Paralogues in human: CHRNA4 (50% identical), CHRNA3 (49% identical), CHRNA2 (48% identical), CHRNA6 (46% identical), CHRNA5 (44% identical), CHRNB3 (42% identical), CHRNB4 (42% identical), CHRNB2 (41% identical), CHRNB1 (37% identical), CHRNA7 (37% identical), CHRND (36% identical), CHRNG (35% identical), and 33 more.